SP140 (SP140 nuclear body protein)
Diseases named in the same sentence as SP140 in open-access papers (continued):
Sharing a sentence is not in itself a finding about the gene and the disease.
sleep disordered breathing (1 paper, 2024). "In patients with sleep disordered breathing and excessive daytime sleepiness, SP140 promoter methylation (−194 CpG site) was increased, and SP140 protein levels were decreased." (PMID 38468469, 2024).
tumor (11 papers, 2012 to 2025). "Based on recent studies, SP140 enhances STAT1 signaling in tumor-associated macrophages, which subsequently increases the expression of PD-L1." (PMID 41188771, 2025). "SP140 is also an epigenetic reader that skews inflammation-related transcriptional programs in tumor-associated macrophages (TAMs)." (PMID 41188771, 2025). "Complementary studies show that tumors with an SP profile dynamically regulate PD-L1, and where SP140 is present, PD-L1 levels on tumor-associated macrophages facilitate immunosuppression and predict responses to anti-PD-1/PD-L1 therapies." (PMID 41188771, 2025). "Interestingly, elevated SP140 expression correlates with higher tumor mutation burden, improved survival, and more favorable responses to immunotherapy." (PMID 41417432, 2025). "By elevating PD-L1 levels, SP140 promotes immune evasion, reduces T cell activity, and contributes to tumor progression." (PMID 41188771, 2025). "The tumor microenvironment is formed by SP140, a chromatin reader that is primarily expressed in immune cells and controls immunological checkpoints." (PMID 41188771, 2025). "SP140-high tumors possess increased PD-L1 transcription levels as SP140 acts to facilitate an immunosuppressive tumor microenvironment." (PMID 41188771, 2025). "The findings revealed positive correlations between the expression levels of SP100/SP110/SP140 and most tumor-infiltrating immune cells, including activated B cells, Tcm cells, CD8 T cells, and NKT cells." (PMID 37354211, 2023). "Loss of SP140 in CESC cells downregulated the DNA repair gene FBXO6, which resulted an increased DNA repair and decreased generation of tumor-specific antigens." (PMID 35368888, 2022). "Thus, when SP140 is dysregulated, its powers of gene silencing on immune-relevant genes can be co-opted for tumor-promoting inflammatory signaling instead." (PMID 41188771, 2025). "SP140’s overexpression may enhance immune responses in the tumor microenvironment, while SP100’s downregulation disrupts differentiation via transcriptional/translational suppression, leading to initiation and progression of tumorigenesis." (PMID 41188771, 2025). "Additionally, a higher proportion of PAAD patients with elevated SP140 expression had a history of smoking and tumors located in the head of the pancreas, suggesting potential links between SP140 expression, smoking behavior, and tumor localization." (PMID 37354211, 2023). "Mutation or deletion of SP140 was predictive for shorter PFS and OS and associated with SOX11 expression, suggesting this gene may be a potential tumor suppressor in MCL." (PMID 34882582, 2022). "Homology with SP100 also suggests that SP140 may exert tumor suppressor activity." (PMID 22235315, 2012). "We found a striking positive correlation between the SP subfamily of Bromodomain proteins, namely SP100, SP100, SP140, and SP140L, and the estimate score across all analyzed tumor types." (PMID 36614001, 2022). "Here, we demonstrate a significant correlation between SP100, SP110, SP140, and SP140L genes’ expression and immune cell populations in the tumor microenvironment." (PMID 36614001, 2022). "KAT2A, SP140 and BRD9 protein expression was higher in tumor tissues, and SMARCA2, BRPF3, KAT2B and EP300 protein expression was lower in the tumor tissues." (PMID 34149798, 2021). "SP140 and SP100 can influence gene programs in macrophages and dendritic cells; thus, they would also likely influence PD-L1 expression as well as pro-inflammatory signaling in the tumor microenvironment." (PMID 41188771, 2025). "This systematic review underscores the dual oncogenic and tumor-suppressive roles of SP100 family proteins (SP100, SP110, SP140, SP140L) across 25 cancer types, shaped by context-dependent expression patterns, genetic/epigenetic alterations, and possible interactions with tumor microenvironments." (PMID 41188771, 2025).
tumor (continued). "The expression of most BrD members significantly negatively correlated with cancer stemness across many TCGA tumor types, although only for KAT2B, KMT2A, SMARCA2, BAZ2B, SP100 and SP140, the association was highly consistent (regardless of the tumor type)." (PMID 35049055, 2022). "Although experimental validation is needed, the tumor suppressors/pro-apoptotic factors, MZF1 and the ubiquitous transcription factor STAT1 may be biologically relevant as decreased binding interactions might lower SP140 expression." (PMID 22235315, 2012). "We stratified basal tumours in Take and No Take groups and noted that the expression of ZNF831, IKZF3 and SP140 was lower in the Take compared with the No Take group (p < 0.05)." (PMID 28588211, 2017).
infection (9 papers, 2021 to 2025). The state of being infected such as from the introduction of a foreign agent such as serum, vaccine, antigenic substance or organism. "We examined the effect of type I IFN both in WT B6 mice and in Sp140−/− mice that are highly susceptible to infection because of an excessive type I IFN response to infection." (PMID 40463021, 2025). "Macrophages from Sp140−/− mice that are highly susceptible to infection produce excessive type I IFN upon immune stimulation, recapitulating the high type I IFN/low IL-1 signaling phenotype of these animals in vivo." (PMID 40937719, 2025). "In SP110- and/or SP140-knockdown macrophages, genes associated with inflammatory responses were also upregulated upon infection with M. tuberculosis." (PMID 39162523, 2024). "We generated Sp140–/– mice and found that they are susceptible to infection by Legionella pneumophila and Mycobacterium tuberculosis." (PMID 34151776, 2021). "Loss of Ifnar protected Sp140–/– mice from weight loss and reduced bacterial burdens at day 25 post-infection, similar to those seen in B6 mice." (PMID 34151776, 2021). "The increased susceptibility of Sp140–/– mice was accompanied by significant weight loss and shortened survival upon infection with M. tuberculosis, again phenocopying the B6.Sst1S mice." (PMID 34151776, 2021). "In addition, similar to C3HeB/FeJ mice, Sp140 KO mice also exhibit increased susceptibility to M. tuberculosis infection, indicating that Sp140 is a key determinant of host vulnerability to the infection." (PMID 40843005, 2025). "Downregulation of the transcriptional regulatory genes Sp110 and Sp140 in C3HeB/FeJ mice has been demonstrated to activate gene expression associated with inflammatory responses during M. tuberculosis infection, resulting in susceptibility to the infection." (PMID 39162523, 2024). "However, the exact mechanisms causing the infection-induced differences in myeloid cells from Sp140−/− mice was unclear, and thus required more in-depth profiling of the myeloid compartment." (PMID 38029747, 2023). "We also observed that Sp140−/− BMMs exhibited higher Ifnb1 transcript levels than WT cells after MHV68-GFP infection." (PMID 40500448, 2025). "We used RNA sequencing to analyze the global gene expression patterns in M. tuberculosis-infected lungs of B6, Sp110–/–, Sp140–/–, and B6.Sst1S mice at day 28 post-infection." (PMID 34151776, 2021). "When infected with M. tuberculosis, however, Sp140–/– mice exhibited high bacterial burdens in their lungs, similar to B6.Sst1S mice and significantly greater than B6, Sp110–/– or Sp140+/– littermate mice at day 28 post-infection." (PMID 34151776, 2021). "In contrast, in Sp140−/− mice on the C57BL/6 background, which express high levels of type I IFN after Mtb infection and develop necrotic pulmonary lesions, MLKL-deficiency reduced bacterial burden and pathology after high-dose infection." (PMID 40950000, 2025). "Furthermore, the correlation between diverse lymphocyte and myeloid populations and other DE-CRs (JAK2 and SP140) suggests that epigenetic modulation plays a more extensive role in determining the identity, recruitment, and functional capacity of immune cells during infection." (PMID 41290882, 2025). "As expected, both Sp140−/− and Ifng−/− mice had up to 10-fold higher CFU than WT mice while Ifnar1−/−, Sp140−/−Ifnar1−/−, and Tbet−/− mice were as resistant as WT mice at 3 weeks post infection." (PMID 40463021, 2025). "The antiviral effect of SP140 was independent of IFN-I signalling, as Sp140−/−Ifnar−/− BMMs also exhibited higher levels of infection compared with Ifnar−/− BMMs." (PMID 40500448, 2025). "We found that Sp140–/– and B6.Sst1S lungs showed moderately increased granulocyte infiltration by 25 days post infection, with apparently more severe infiltration in Sp140–/– mice than in B6.Sst1S mice, though this difference is not statistically significant." (PMID 34151776, 2021).
infection (continued). "Considering that cell viability and growth rate were not changed by SP110 and/or SP140 knockdown at 24 and 48 h p.i., ATP concentration in macrophages would not be affected by the depletion of SP110 and/or SP140 in the early infection period." (PMID 39162523, 2024).
cancer (8 papers, 2019 to 2025). A tumor composed of atypical neoplastic, often pleomorphic cells that invade other tissues. "As new research around nuclear proteins continues, the importance of the SP100 family, especially SP140, in cancer immunity and epigenetic regulation is growing." (PMID 41188771, 2025). "Mechanistically, SP140 mutations caused downregulation of BCR signaling and MYC targets, leading to cancer progression and poor prognosis." (PMID 41188771, 2025). "SP140 was the most frequently studied family member, appearing in 17 studies across several cancers." (PMID 41188771, 2025). "Additionally, SP140 is highly expressed in TAMs across multiple cancer types, including HNSCC." (PMID 41417432, 2025). "This systematic review analyzed 29 studies (2004–2024) to evaluate the dual roles of SP100 family proteins (SP100, SP110, SP140, SP140L) across 25 cancer types." (PMID 41188771, 2025). "After RAYYAN-assisted deduplication and screening, studies analyzing SP100, SP110, SP140, or SP140L alterations in human cancers (excluding cell lines studies) were included." (PMID 41188771, 2025). "The Speckled Protein 100 (SP100) family, comprising SP100, SP110, SP140, and SP140L, has emerged as a critical player in cancer biology due to their roles in transcriptional regulation, chromatin modification, and immune signaling." (PMID 41188771, 2025). "Mechanistic studies targeting SP140’s immune pathways (e.g., PD-L1, TRIM22) and SP100’s DNA repair functions in underrepresented cancers (e.g., BLCA, OSCC) could refine therapeutic applications." (PMID 41188771, 2025).
bacterial infections (5 papers, 2021 to 2025). "We previously found a critical role for SP140 in the repression of IFN-I in vivo, as Sp140−/− mice are highly susceptible to multiple bacterial infections due to elevated IFN-I4." (PMID 40500448, 2025). "Similar to B6.Sst1S mice, Sp140–/– mice exhibit an exacerbated type I IFN response after bacterial infection, and the susceptibility of Sp140–/– mice is rescued by crosses to Ifnar–/– mice." (PMID 34151776, 2021). "Our data suggest that deletion of Sp140 is sufficient to recapitulate the full Sst1S phenotype including broad susceptibility to multiple bacterial infections, including M. tuberculosis and L. pneumophila." (PMID 34151776, 2021). "Our results suggest that loss of Sp140 explains the susceptibility to bacterial infections associated with the Sst1S haplotype." (PMID 34151776, 2021). "Here we provide evidence that Sp140 is a gene encoded within the Sst1 locus that represses type I IFN transcription during bacterial infections." (PMID 34151776, 2021). "Overall, we therefore conclude that loss of Sp140 likely explains the Sst1-linked hyper type I IFN-driven susceptibility to bacterial infections." (PMID 34151776, 2021). "A causative role for type I IFNs in the phenotype of Sp140–/– and Sst1S mice was seen in the reduced susceptibility of Sp140–/– Ifnar–/– and B6.Sst1S Ifnar–/– mice to bacterial infection." (PMID 34151776, 2021). "To test whether loss of Sp140 might account for the susceptibility of Sst1S mice to bacterial infections, we generated Sp140–/– mice." (PMID 34151776, 2021). "Our results implicate Sp140 as an important negative regulator of type I IFNs that is essential for resistance to bacterial infections." (PMID 34151776, 2021). "Collectively our results strongly suggest that the lack of expression of Sp140 in B6.Sst1S mice explains the broad susceptibility of these mice to bacterial infections." (PMID 34151776, 2021). "Susceptibility of Sp140–/– mice to bacterial infection was rescued by crosses to mice lacking the type I IFN receptor (Ifnar–/–)." (PMID 34151776, 2021). "Sp140–/– mice have elevated Ifnb transcripts during bacterial infection." (PMID 34151776, 2021). "Interestingly, SP140 which is an important negative regulator of Type I IFN and an essential transcriptional regulator for resistance to bacterial infections, was one of the most significant predicted TF for the downregulated genes." (PMID 40762982, 2025). "Although the mechanisms associated with SP140 were not fully elucidated, these results suggest SP140 as a novel regulator of type I IFN induction that is crucial for resistance to bacterial infections." (PMID 35011636, 2021). "Another major question is whether or how the repression of type I IFNs by SP140 is specific for bacterial infections and, if not, whether the presence of SP140 impairs anti-viral immunity." (PMID 34151776, 2021).
hematologic malignancies (1 paper, 2025). "Collectively, these hematologic malignancies illustrate the SP100 family’s involvement in immune modulation and genomic stability, with SP140 emerging as a key player." (PMID 41188771, 2025).
SP140 also shares sentences with these, for which no sentence is quoted: systemic lupus erythematosus (2 papers); acute myelogenous leukemia (1); allergic disease (1); appendicitis (1); Autoimmunity (1); breast carcinoma (1); gastric cancer (1); glioblastoma (1); graft versus host disease (1); Granuloma (1); gynecologic cancers (1); Hashimoto thyroiditis (1); head and neck neoplasm (1); immunodeficiency syndromes (1); latent infection (1); melanoma (1); oral squamous cell carcinoma (1); ovarian carcinoma (1); pancreatic adenocarcinoma (1); pneumonia (1); psoriatic arthritis (1); sarcoidosis (1); Sjogren syndrome (1); tongue cancer (1).